CD4 (CD4 molecule)
Diseases named in the same sentence as CD4 in open-access papers (continued):
Sharing a sentence is not in itself a finding about the gene and the disease.
AIDS (continued). "A case of chest wall abscess due to Salmonella enterica serovar Dublin, another nontyphoidal serovar, has been reported in a patient with a history of uncontrolled acquired immunodeficiency syndrome (AIDS) (CD4 count of 71 cells/uL)." (PMID 38053106, 2023). "In multivariable analysis, SCT (adjusted odds ratio 1.62 [95% CI 1.14–2.32]) and APOL1 high-risk genotypes (4.88 [3.57–6.67]) as well as age, prior AIDS, recent CD4 cell count, diabetes, and cardiovascular disease remained associated with eGFR <60 ml/min per 1.73 m2." (PMID 35257059, 2022). "The hallmark of the acquired immunodeficiency syndrome (AIDS), caused by the human immunodeficiency virus (HIV) infection, is accompanied by continued HIV replication and profound decline of circulating CD4+ T lymphocyte cells." (PMID 35154126, 2022). "Additionally, low CD4 T lymphocyte count was associated with high frequency of encephalitis caused by toxoplasmosis in patients who developed AIDS." (PMID 36504775, 2022). "Acquired immunodeficiency syndrome (AIDS) is defined as less than 200 CD4 T-cells per liter of blood or as a disease that defines AIDS." (PMID 36389792, 2022). "CD4 T-cell decline is a risk factor for developing AIDS-related KS." (PMID 35626397, 2022). "HIV-1 preferentially infects CD4+ T cells, macrophages, and microglial cells, leading to a damaged immune system and the development of acquired immunodeficiency syndrome (AIDS)." (PMID 36275462, 2022). "HIV/AIDS patients with higher circulating IFN-γ were associated with poor CD4+ T-cell recovery." (PMID 35154126, 2022). "HIV is a retrovirus known to infect CD4+ T cells and macrophages, causing a slow depletion of the immune cell pool and eventually leading to the acquired immunodeficiency syndrome (AIDS) if left untreated." (PMID 36146833, 2022). "HIV is a retrovirus that primarily infects CD4+ T lymphocytes, leading to a progressive decline in their number, gradually weakening the host’s immune system leading to acquired immune deficiency syndrome (AIDS)." (PMID 35646738, 2022). "A 2016 report showing an association with pathogenesis reported a decreased CD4 T-cell count in the peripheral blood coupled with an elevated intestinal adenovirus (sequencing) and Enterobacteriaceae, contributing to AIDS-related intestinal disease and disease progression." (PMID 35632692, 2022). "The suboptimal CD4+ T-cell recovery has been proved to be associated with a substantial increase in the risk of mortality, and AIDS-related and non-AIDS-related morbidity, calling for the urgency of investigating the underlying mechanisms of INR and developing relevant interventions." (PMID 35154126, 2022). "A meta-analysis evaluating CD4+ T cells levels and viral load in children as predictors of disease progression found that children older than two years old had an increased risk of progression to AIDS when the CD4+ T cell percentages were below 15% and when the viral load exceeded 105 copies per mL." (PMID 36016383, 2022). "Fast replicating X4 viruses have long been associated with faster CD4 decline, and the risk of AIDS progression could be as much as 3.8 × higher, which in real terms translates to multiple years of additional lost life." (PMID 36514107, 2022). "These estimates suggested that CD4/CD8 ratio ≤ 0.4 could be associated with serious non-AIDS events." (PMID 35428209, 2022). "However, to date, only a limited number of parasites, such as Cryptosporidium spp., E. bieneusi, and E. histolytica, have been defined as AIDS-associated, and such infections are correlated with low CD4+ T cell counts." (PMID 36067140, 2022). "These factors, as well as AIDS status, menopause status, age, and height, were added into a multivariable regression model, which revealed that employment and CD4+ cell count was associated with a higher mental component, while moderate/high physical activity was associated with a lower one." (PMID 35679332, 2022).
AIDS (continued). "HIV can infect CD4-expressing immune cells and eventually cause AIDS." (PMID 36278485, 2022). "Carriage of the KIR3DS1 + HLA-Bw4*80I allele combination, associated with slower time to AIDS produces NK cells with a superior ability to suppress HIV replication in autologous HIV-infected CD4 cells compared to carriers of either the receptor or ligand alone or neither." (PMID 35720328, 2022). "To account for inherent variations in baseline CD4 counts, we constructed a metric to quantify the extent of progression to AIDS as the ratio of the reduction in measured CD4 counts from baseline and the reduction associated with AIDS." (PMID 35271687, 2022). "This participant had a VL of 148,244 and a CD4 count of 41, indicative of acquired immunodeficiency syndrome and probable ART failure." (PMID 35923140, 2022). "The deterioration of CD4+ T cells below critical levels renders the body susceptible to opportunistic infections (OIs) and the advancement of acquired immunodeficiency syndrome (AIDS)." (PMID 35814023, 2022). "When the CD4 T cell count drops to around 200 cells/mm3 of blood, these individuals enter the final stage of the infection, the acquired immunodeficiency syndrome (AIDS), eight to ten years after infection." (PMID 36423132, 2022). "The discrepancy with our results may depend on the different definition of non-AIDS events, while, in line with our findings, the authors observed that low CD4/CD8 ratio was associated with increased risk of non-AIDS defining cancers." (PMID 35428209, 2022). "CD4 lymphocyte counts of 50 cells/μL or less have been clinically used to guide CMVR screening in HIV-positive and acquired immune deficiency syndrome patients, leading to rapid treatment and an improved prognosis for CMVR in these populations." (PMID 35694535, 2022). "Interestingly, stratified analysis showed that the frequency of rs1001581 C allele was significantly higher in AIDS patients with the CD4+ T-lymphocyte count <200 cells/μl than those with >200 cells/μl (p = 0.022)." (PMID 35368687, 2022). "The oral lesions of C. albicans are among the first signs of acquired immune deficiency syndrome (AIDS) in patients infected with humanimmunodeficiency virus (HIV), indicating disease progression and reduction of CD4+ lymphocytes." (PMID 36654790, 2022). "In general, AIDS and/or low CD4 cell count at baseline are associated with more advanced disease and excessive weight gains may reflect either a “return-to-health” effect or, in some cases, overcompensation for poor pre-ART health status." (PMID 36016299, 2022). "Given that elevated IP-10 levels were found to be associated with CD4+ T cell decline and an increased risk of rapid progression towards AIDS, the reduction in blood IP-10 levels may signal successful antiretroviral treatment." (PMID 35456158, 2022). "We identify that PWH virally suppressed on ARTs that live severely immunosuppressed with greater percentage of time have a significantly increased risk of mortality (27%, 95%CI 19%-35%) and of serious non-AIDS-defining events (11%, 95%CI 7%-14%) even after adjusting for updated CD4 counts." (PMID 35602655, 2022). "Pneumonia with interstitial infiltrates in the setting of advanced CD4 lymphocyte depletion is the most common clinical syndrome caused by B bronchiseptica in patients with HIV/AIDS, and may be accompanied by sepsis." (PMID 34941094, 2021). "The hallmark of HIV/AIDS is a gradual depletion of CD4 T cells." (PMID 34017335, 2021). "HIV mainly attacks CD4+ T lymphocytes, causing a progressive decrease in the number of CD4+ T lymphocytes, resulting in impairment of the body's cellular immune function, and finally to the onset of AIDS." (PMID 33820568, 2021). "Patients who present late with HIV-1, the so-called late presenters (LP) are defined as patients with CD4+ T-cell count below 350 cells/μL or the presence of an acquired immunodeficiency syndrome (AIDS)-defining illness upon HIV diagnosis." (PMID 34823639, 2021).
AIDS (continued). "Finally, within the PLWH group, being a long sleeper per 24 h (total sleep time > 8 h including more and long daytime naps) was associated with a greater severity of the disease (lower CD4 nadir and more frequent history of AIDS-defining events)." (PMID 33429860, 2021). "In addition, previous AIDS diagnosis, lower current CD4 counts and suboptimal treatment adherence were associated with having an AIDS event/mortality in our study group." (PMID 34021711, 2021). "The 24-month combined clinical immuno-virological outcome was defined as unfavorable when either death, loss to follow-up, progression to WHO-AIDS stage, a decrease of CD4 count >10% compared to baseline, or a detectable viral load (VL > 50 copies/mL) occurred at 24 months." (PMID 34277512, 2021). "A prior AIDS diagnosis was much less prevalent in those hospitalised for injury/poisoning (28%) compared to other common causes and hospitalisations overall (51%); similarly, CD4 nadir was higher for the injury/poising cause." (PMID 33926373, 2021). "Collectively, the high prevalence of risky maladaptive practices, psychological stressors and HIV/AIDS-associated perpetual immunocompromised state (low CD4 count), may put LGBTQ+ Living with HIV/AIDS at a much higher risk of contracting COVID-19." (PMID 34017893, 2021). "Higher baseline CD4+ cell counts were associated with lower AIDS-related mortality." (PMID 34592916, 2021). "Infection of CD4+ T cells by the human immunodeficiency virus type 1 (HIV-1) leads to a drastic decrease in their number and causes acquired immune deficiency syndrome (AIDS), which can eventually lead to death." (PMID 33669676, 2021). "CD4+ T cells are the physiological target of HIV-1 and depletion of this cell type by HIV-1 causes acquired immunodeficiency syndrome." (PMID 33476323, 2021). "Access to ART has dramatically reduced incidence of several opportunistic infections (e.g. Pneumocystis pneumonia, Cytomegalovirus) that are important causes of death in people with low CD4+T cell count due to progression to Acquired Immune Deficiency Syndrome (AIDS)." (PMID 34134725, 2021). "Human immunodeficiency virus (HIV) infection depletes CD4+ T cells, leading to the development of acquired immunodeficiency syndrome (AIDS), AIDS-defining opportunistic infections or cancer." (PMID 34344350, 2021). "While a study explained that no HIV-related variables predicted OHRQoL, other investigations showed that the factors indicating the severity of HIV infection such as viral load, CD4 cell counts, and AIDS diagnosis were significantly associated with the patients' OHRQoL." (PMID 34134683, 2021). "In the absence of antiretroviral therapy (ART), initial viral load and CD4 count serve as a way to estimate how likely a patient is to progress from HIV to acquired immunodeficiency syndrome (AIDS) (classically defined as a CD4 count of <200)." (PMID 34094761, 2021). "For individuals with HIV-HBV co-infection, this list extends to HIV-related characteristics, such as CD4+ T-cell counts and acquired immunodeficiency syndrome (AIDS)-defining illnesses." (PMID 34372547, 2021). "Lower CD4 count was shown to be associated with new AIDS events or death in our study." (PMID 34021711, 2021). "CD4+ T lymphocytes are significant targets of HIV, with their progressive death culminating in acquired immune deficiency syndrome (AIDS)." (PMID 34925380, 2021). "In fact, AIDS patients with low CD4+ T cell counts have a high risk of developing NTM infection." (PMID 34835191, 2021). "However, these non-AIDS comorbidities are associated with low CD4+ T-cell levels and are thus frequent in InRs—unable to restore proper CD4+ T-cell levels—that represent 20% of HIV-infected individuals." (PMID 35222352, 2021). "The source of the IL-17 may be CD4+ T helper 17 (Th17) cells, a view supported by the observations that CD4-depleted HIV/AIDS patients, and Th17-deficient patients are very susceptible to oral candidosis." (PMID 34356934, 2021).
AIDS (continued). "Human immunodeficiency virus type 1 (HIV-1) is a lentivirus in the retrovirus family that causes chronic infection, leading to the gradual depletion of CD4+ T cells and acquired immunodeficiency syndrome (AIDS) if untreated." (PMID 34835043, 2021). "Two larger Euromerican cohort studies (633 and 423 participants, respectively) studied the contributions of mtDNA mutations at a resolution of the composite haplogroup and/or individual variant to AIDS progression/CD4+T-cell recovery, both using CD4+T-cell counts as outcomes." (PMID 34970271, 2021). "Similarly, two smaller European studies (469 participants with cross-sectional design and 275 participants with cohort design, respectively) studied the associations between mtDNA haplogroups and AIDS progression/CD4+T cell recovery." (PMID 34970271, 2021). "Antiretroviral therapy made it possible to decrease the viral load below the sensitivity limit of diagnostic tests, caused an increase in the level of CD4 lymphocytes, and reduced the incidence of opportunistic infections and the development of full-blown acquired immunodeficiency syndrome (AIDS)." (PMID 34373766, 2021). "On the other hand, among various steps in T-lineage development, the functional and numerical alteration of CD34+ LPs in HIV-1 infection needs to be further elucidated to improve the current understanding of the degree of impaired CD4+ T-cell generation on peripheral CD4+ T-cell loss and AIDS onset." (PMID 32154191, 2020). "Thus, HIV mainly targets CD4+ T cells and can lead acquired immune deficiency syndrome (AIDS) by disarming the host immune system." (PMID 33396586, 2020). "Human immunodeficiency virus (HIV) causes acquired immune deficiency syndrome (AIDS) and enters the host cell via CD4 and either CC-chemokine receptor 5 (CCR) or CXC-chemokine receptor 4 (CXCR4)." (PMID 33396586, 2020). "Activation, infection, and eventual depletion of human immunodeficiency virus (HIV)-specific cluster of differentiation 4 (CD4) T cells are the crucial pathogenetic events in acquired immunodeficiency syndrome (AIDS)." (PMID 32462053, 2020). "The human immunodeficiency virus (HIV) causes infection and acquired immunodeficiency syndrome (AIDS) and destroy CD4+ T-lymphocytes in the blood." (PMID 32630535, 2020). "Acquired immunodeficiency syndrome (AIDS) is a serious infectious disease caused by the human immunodeficiency virus (HIV), which mainly invades the immune system (particularly on CD4+ T lymphocytes, monocyte macrophages, and dendritic cells)." (PMID 33317484, 2020). "Different CD4+ T cell numbers associated with PCP infection in HIV/AIDS patients." (PMID 32911508, 2020). "One example that strongly supports the importance of a protective cellular response against M. tb is individuals with the acquired immunodeficiency syndrome (AIDS), who have increased susceptibility to M. tb due to a deficiency of CD4+ T cells." (PMID 33207695, 2020). "In addition, HIV-1 infection and the progression to full-blown AIDS is recognized to cause a depletion in CD4+ T-cells." (PMID 32824563, 2020). "Several studies have demonstrated that HCQ in human immunodeficiency virus/acquired immunodeficiency syndrome (HIV/AIDS) patients stabilized CD4 T-cell counts or elevation when used in combination with hydroxyurea as well as didanosine." (PMID 33062720, 2020). "During the progression to AIDS, T. gondii reactivation results in encephalitis, and the progressive loss of CD4 T cells is associated with the progression of toxoplasmosis, supporting the relevance of CD4 T cell-mediated immunity." (PMID 32669460, 2020). "In addition, a lower CD4 count is known to be associated with a higher risk of a new AIDS defining illness, and overall mortality, even after viral suppression on ART." (PMID 33129258, 2020). "The common risk factors in the two groups were nadir CD4+ T-cell counts, whether on-cART, and having one of the following comorbidities: Pneumocystis pneumonia, non-AIDS malignancy, and kidney disease." (PMID 33681235, 2020).
AIDS (continued). "Some authors have observed that a lower CD4+/CD8+ ratio in HIV-infected patients was associated with an increased risk of AIDS events and AIDS-related death, but a recent observational cohort of virologically suppressed patients observed a little evidence for non-AIDS mortality." (PMID 31945066, 2020). "The acquired immunodeficiency syndrome (AIDS) is caused by HIV, which infects and depletes CD4+ T cells in the patients." (PMID 32792548, 2020). "These genes could represent novel candidates for immunotherapies targeting pathways associated with non-AIDS-related comorbidity and/or abnormal immune activation of CD4 + T cells." (PMID 33298174, 2020). "Human immunodeficiency virus-1 (HIV-1) is the causative agent of acquired immunodeficiency syndrome (AIDS) and mainly infects CD4-positive (CD4+) immune cells, progressively damaging the immune system." (PMID 31985356, 2020). "We found that both groups shared common risk factors for death, and these factors included nadir CD4+ T-cell counts, whether on-cART, and having one of the following comorbidities: Pneumocystis pneumonia, non-AIDS malignancy, and kidney disease." (PMID 33681235, 2020). "In persons living with human immunodeficiency virus (HIV), toxoplasmosis occurs when CD4 counts are very low and is considered an acquired immunodeficiency syndrome (AIDS) defining illness." (PMID 32148982, 2020). "Low CD4 count and AIDS are risk factors for HIV-infected people suffering from AKI." (PMID 32160882, 2020). "Currently the most used is the Adapted CDC: Existence of two reagent screening tests or one confirmatory for detection of anti-HIV antibodies + Evidence of immunodeficiency: diagnosis of at least one disease indicative of AIDS and/or T CD4+ lymphocyte count less than 350 cells/mm3." (PMID 32953363, 2020). "As the AIDS epidemic unfolded, the appearance of opportunistic infections in at-risk persons provided clues to the underlying problem: a dramatic defect in cell-mediated immunity associated with infection and depletion of CD4+ T lymphocytes." (PMID 31552045, 2019). "The association of miR‐375 changes and CD4 cell counts might explain the opposite trend between asymptomatic and AIDS‐KS patients and the discordant cases." (PMID 30549196, 2019). "Similarly to HIV-1, HIV-2 causes AIDS, but with lower rates of transmission, CD4+ T-cell decline, and disease progression." (PMID 30622192, 2019). "However, HIV/AIDS patients with CD4+ T cell counts <100 cells/μL are at risk of Cryptococcosis and the situation is worse in those who are not taking ART." (PMID 31805085, 2019). "Human Immunodeficiency Virus (HIV) destroys CD4 cell count, which result to an increased plasma HIV RNA levels and experience an Acquired Immune Deficiency Syndrome (AIDS) in the long-run." (PMID 31291281, 2019). "Untreated human immunodeficiency virus (HIV) depletes its host CD4 cells, ultimately leading to acquired immunodeficiency syndrome (AIDS)." (PMID 32009881, 2019). "Strikingly, even those with recovery of near-normal CD4+ T cell counts may maintain chronic immune activation that has been linked to an increased risk of non-AIDS-related morbidity and mortality." (PMID 31319498, 2019). "Anti-retroviral therapy causes a decline in the incidence of several AIDS defining conditions, most clearly in the case of TB, but full immune recovery is only achieved if treatment is started immediately after infection when CD4+ cell counts are still high." (PMID 31059528, 2019). "Type 1 HIV (HIV‐1), the etiologic agent of acquired immune deficiency syndrome (AIDS), is a member of the retrovirus family that preferentially infects activated CD4+ T lymphocytes." (PMID 31552706, 2019). "The coexistence of both pathologies in this patient strongly suggested an acquired immunodeficiency syndrome, despite a relatively high CD4 count." (PMID 30867046, 2019).